RNU6-219P (RNA, U6 small nuclear 219, pseudogene)
Gene: Small nuclear RNA gene on chromosome 18 (58,805,268 to 58,805,374, forward strand). Ensembl gene ENSG00000201598.
Homologues: Orthologues: chimpanzee U6 (100% identical), macaque U6 (95% identical), pig U6 (79% identical), dog U6 (76% identical), rat LOC120095714 (70% identical), mouse Gm54984 (68% identical), pig U6 (67% identical), mouse Gm24164 (66% identical), guinea pig U6 (64% identical), pig U6 (64% identical). Paralogues in human: RNU6-393P (87% identical), RNU6-589P (87% identical), RNU6-1011P (86% identical), RNU6-1145P (86% identical), RNU6-166P (86% identical), RNU6-38P (86% identical), RNU6-41P (86% identical), RNU6-15P (85% identical), RNU6-31P (85% identical), RNU6-44P (85% identical), RNU6-639P (85% identical), RNU6-73P (85% identical), and 1287 more.